LINC02249 (long independently transcribed non-coding RNA 2249)
Synonyms: DKFZp434L187
Gene: Long non-coding RNA gene on chromosome 15 (30,195,583 to 30,373,471, forward strand). Ensembl gene ENSG00000225930.
Diseases named in the same sentence as LINC02249 in open-access papers:
LINC02249 is named in the same sentence as 1 disease in open-access papers, as found by Europe PMC text mining. Sharing a sentence is not in itself a finding about the gene and the disease. The quoted sentences say what the papers report.
cancer (1 paper, 2022). A tumor composed of atypical neoplastic, often pleomorphic cells that invade other tissues. "We observed that LINC02249 was significantly expressed in a variety of human cancers (including SKCM), and its upregulation was related with a poor outcome in SKCM." (PMID 36117849, 2022).